INS (insulin)
Diseases named in the same sentence as INS in open-access papers (continued):
Sharing a sentence is not in itself a finding about the gene and the disease.
diabetic neuropathy (continued). "We previously demonstrated the beneficial consequence of insulin and IGF-1 treatment in preventing diabetic neuropathy in STZ-induced diabetic rats." (PMID 35298717, 2022). "Our results support a similar mechanism of insulin-signaling disruption within DRG neurons, and this modulatory step should be considered as an additional component contributing to diabetic neuropathy." (PMID 21754917, 2011). "The fasting insulin PRS displayed a negative association with neuropathic pain in the whole cohort and in diabetic polyneuropathy subgroup (Pbinary = 0.04, and Pbinary = 0.01)." (PMID 39471050, 2025). "The following parameters showed a statistically significant difference between the groups: waist circumference (p < 0.006), duration of T2D (p < 0.001), BMI (p < 0.041), insulin therapy (p < 0.001), CVD (p < 0.001), diabetic neuropathy (p < 0.001), diabetic foot (p < 0.001), and S-HbA1c (p < 0.001)." (PMID 37626799, 2023). "Due to its role in the clearance of insulin, the identification of drugs that selectively modulate IDE activity toward insulin is proposed by many authors as a promising therapeutic strategy for the cure of TDM2 and of its complications, such as diabetic neuropathy and retinopathy." (PMID 35204815, 2022). "Thus, the preservation or restoration of neuronal insulin signal transduction pathways and IRS2 expression would seem to be a useful avenue for exploring new and improved therapeutic interventions in diabetic neuropathy." (PMID 27514532, 2016). "Complete baseline data on the age, sex, BMI, duration of insulin treatment, HbA1c, daily insulin dose, presence/absence of diabetic neuropathy, smoking, alcohol consumption, and concomitant use of SUs, BGs, α-GIs and TZDs were available for 495 patients." (PMID 26124906, 2015). "Emerging evidence suggests lack of insulin and insulin resistance in sensory nerves might also play a role in development of diabetic neuropathy." (PMID 34319011, 2021). "However, there is currently no satisfactory therapy for insulin-induced diabetic neuropathy." (PMID 40343778, 2025). "Although some of these experiments suggested that impairments in neuronal insulin signaling may contribute to the development of diabetic neuropathy, the role of interactions among insulin, InsRs and the TRPV1 receptors in these processes have not yet been evaluated in detail." (PMID 32260335, 2020). "Painful diabetic neuropathy (PDN) has been estimated to affect 20% to 24% of all patients with DM, and PDN has been reported in 19% of those with insulin-dependent DM and 49% of those with non-insulin-dependent DM." (PMID 34069494, 2021).
overnutrition (117 papers, 2009 to 2025). An imbalanced nutritional status resulting from excessive intake of nutrients. "In contrast, AMPK—a sensor of nutrient stress, normally activated under conditions of energy deficiency—is suppressed by overnutrition, reducing fatty acid oxidation and insulin sensitivity." (PMID 39857433, 2025). "Early overnutrition is associated with cardiometabolic alterations in adulthood, likely attributed to reduced insulin sensitivity due to its crucial role in the cardiovascular system." (PMID 37833890, 2023). "Overnutrition is linked with the changes in protein expression in brain insulin signaling, leading to pathological features in the brain." (PMID 35873818, 2022). "This systematic review and meta‐analysis aimed to investigate the association between maternal overnutrition and offspring's insulin sensitivity—following the Preferred Reporting Items for Systematic Reviews and Meta‐analyses statement." (PMID 32567808, 2020). "They suggest that similar to pancreatic β-cells and insulin, overnutrition itself induces ER stress resulting in uroguanylin loss." (PMID 27214655, 2016). "We speculate that the amelioration of hepatic insulin sensitivity would partly protect from overnutrition-associated chronic inflammation and fibrosis in the livers of Aspg knockout mice." (PMID 40760121, 2025). "Animal studies showed that overnutrition could cause insulin and leptin resistance in the hypothalamus via various pathways (e.g., oxidative stress, neurodegeneration and the activation of hypothalamic IKK beta/NF-kappa B paths)." (PMID 35736455, 2022). "When IR occurs, the ability of insulin to inhibit hepatic glucose is decreased, hepatic gluconeogenesis is increased, may be caused by overnutrition, decreased portal vein insulin/glucagon ratios and/or impaired insulin signaling." (PMID 34093184, 2021). "As insulin signaling in the brain influences feeding behavior, SH‐BC‐893 may also enhance satiety by overcoming central insulin and leptin resistance stemming from the ER stress and inflammation associated with overnutrition." (PMID 34231322, 2021). "Overnutrition has been linked to both insulin (INS) resistance and β-cell dysfunction." (PMID 30116740, 2018). "Overnutrition disturbs key metabolic pathways, including insulin/insulin-like growth factor signaling (IIS), the mammalian target of rapamycin (mTOR), and AMP-activated protein kinase." (PMID 39857433, 2025). "Overnutrition affects key cellular metabolic pathways, including insulin/insulin-like growth factor signaling (IIS), the mammalian target of rapamycin (mTOR), and AMP-activated protein kinase (AMPK)." (PMID 39857433, 2025). "Given that overnutrition disrupts insulin signaling, we measured GRP75 expression in HFD‐induced insulin‐resistant." (PMID 41001747, 2025). "One prominent theory posits that overnutrition drives fat accumulation in adipose tissue and ectopic sites, triggering macrophage infiltration, chronic inflammation, and insulin resistance, which disrupts the balance between lipid catabolism and synthesis." (PMID 40297155, 2025). "In a chronic overnutrition model, glucose-stimulated insulin secretion (GSIS) is impaired, in part due to partial inactivation of SENP1 by oxidative stress." (PMID 38184650, 2024). "In particular, overnutrition, through increased blood glucose and lipids, induces the production of pro-inflammatory mediators that, in turn, interfere with insulin signaling pathways." (PMID 39770945, 2024). "On the other hand, overnutrition leads to a compensatory increase of insulin secretion with adaptations in β-cell stimulus-secretion coupling." (PMID 38184650, 2024). "Taylor postulated that long-term overnutrition (i.e., a positive calorie balance) in humans increases insulin secretion and stimulates ectopic fat deposition in the liver." (PMID 39769002, 2024). "Overnutrition induces β-cell dysfunction affecting insulin secretion through mitochondrial ROS generation and NLRP3 activation." (PMID 37599368, 2023).
overnutrition (continued). "Our recent report also suggested that endothelial-derived ROS plays a role in enhancing whole-body (including BAT) insulin sensitivity in response to short-term overnutrition." (PMID 35557517, 2022). "Maternal obesity and overnutrition results in epigenetic alterations of insulin-signaling molecules." (PMID 34828259, 2021). "Overnutrition leading to chronically overcharged metabolism impacts the insulin biosynthetic pathway, where ER overload and activation of the unfolded protein response pathway (UPR) are affected." (PMID 33801681, 2021). "But only for insulin, we found that restricting individuals with BMI≥28 kg/m2 was effective in reducing the influence of overnutrition." (PMID 33411740, 2021). "White adipose tissue (WAT) insulin action has critical anabolic function and is dysregulated in overnutrition." (PMID 33411692, 2021). "In the context of maternal obesity and overnutrition, metabolic profiles shift more erratically, exposing developing offspring to increased levels of glucose, insulin, leptin, and BCAA leading to altered placental energy transfer." (PMID 35118010, 2021). "In overnutrition, mTOR is activated by glucose, insulin signal, or amino acids, before forming mTOR signaling complex 1 (mTORC1), which inhibits the transcription of lysosomal enzymes and inhibits autophagosome formation." (PMID 32517059, 2020). "In case of prolonged upregulation of insulin levels, such as in response to overnutrition, glucose homeostasis is maintained by mitigating insulin signaling via PI3K/AKT for glucose export from the blood into tissues." (PMID 32819363, 2020). "The reduced Pdx1 expression that was observed in young early overnutrition males and the later development of low islet insulin content, suggests a primary β cell dysfunction induced by early overnutrition." (PMID 30842440, 2019). "Despite an early increase in β cell mass induced by early overnutrition, the β cell dysfunction reflected in the reduced islet insulin content and reduced Pdx1 expression eventually leads to β cell death." (PMID 30842440, 2019). "During nutrient abundance (e.g., overnutrition), and in insulin-resistant or diabetic states, FoxO1 modulates the oxidation of glucose via pyruvate dehydrogenase kinase 4 (PDK4)." (PMID 29484207, 2018). "Previous studies have shown that amino acid metabolism, specifically BCAA concentrations, are elevated in response to overnutrition and can affect both insulin sensitivity and secretion." (PMID 30065264, 2018). "As an example, overnutrition during lactation can result in epigenetic modifications in key genes that are known to be involved in the insulin signaling pathway in skeletal muscle that can manifest as impaired insulin sensitivity in later life." (PMID 28993758, 2017). "F yearlings were more insulin resistant at 19 months compared to B yearlings but B yearlings were affected more severely by overnutrition with reduced insulin sensitivity." (PMID 28081146, 2017). "Both under- and overnutrition of prospective mothers set a trajectory in offspring toward increased adiposity, hyperphagia and dysfunction of insulin and glucose responsiveness, and homeostasis." (PMID 28298279, 2017). "In adipocytes, free fatty acids appear to mediate the overnutrition effects on insulin signaling, as they do it in myocytes." (PMID 28912810, 2017). "There were some additional effects of exposure to maternal overnutrition at 3 months which were sex-specific, with reduced insulin levels in males and reduced HOMA-IR in females, suggesting increased insulin sensitivity." (PMID 25082159, 2014). "In brief, mTORC1 activation leads to the formation of an mTOR↔AT2R signaling loop that can serve as a protective feedback mechanism to balance enhanced mTORC1 signaling in cardiac tissue in conditions of overnutrition-induced INS resistance and RAS activation." (PMID 21977024, 2012).
overnutrition (continued). "Overnutrition results in chronic exposure of cardiovascular (CV) tissues to circulating nutrients, glucose, and INS." (PMID 21977024, 2012). "Mice deficient in S6K1, though they have a small body size and reduced β-cell mass, are protected from INS resistance in conditions of overnutrition." (PMID 21977024, 2012). "Our recent findings support the notion that in the setting of overnutrition-induced impairment of cardiac INS metabolic signaling, mTORC1 signaling is carefully controlled by protective feedback mechanisms." (PMID 21977024, 2012). "The mTOR Complex 1 (mTORC1) serves as a converging point for signals from nutrients, INS and Ang II, and is frequently activated in CV tissues in conditions of overnutrition and aging." (PMID 21977024, 2012). "We conclude that acute bouts of overnutrition lead to early changes at the cellular level before whole-body insulin sensitivity is altered." (PMID 19781106, 2009). "We conclude that acute bouts of overnutrition lead to changes at the cellular level before whole-body insulin sensitivity is altered." (PMID 19781106, 2009). "It is possible that a longer duration of overnutrition is necessary to impact whole-body insulin sensitivity." (PMID 19781106, 2009). "Chronic overnutrition may trigger different myocellular mechanisms proposed to contribute to insulin resistance and aggravate skeletal muscle atrophy and dysfunction." (PMID 40064750, 2025). "To model the vascular effects of overnutrition in WD-fed mice, we cultured human dermal microvascular endothelial cells (HDMECs) under diet-mimicking conditions for 6 days, using a mixture of 100 μM palmitate, 25 mM d-glucose, and 1 μM insulin (Pal/Glu/Ins)." (PMID 40488531, 2025). "High birth weight (HBW), linked to maternal overnutrition, may cause excessive fetal adiposity and β-cell dysfunction, promoting MUHO via insulin resistance." (PMID 40662170, 2025). "Insulin action in subcutaneous fat cells is dysregulated by overnutrition with a high fat diet." (PMID 41009753, 2025). "Key therapeutic avenues to mitigate the effects of overnutrition and lipotoxicity include nutritional counseling, lifestyle modifications, weight management strategies, and the judicious use of medications targeting lipid levels and insulin sensitivity." (PMID 38666853, 2024). "Epigenetic modifications in response to overnutrition may lead to permanent alterations (imprinting) of genes involved in glucose-stimulated insulin secretion." (PMID 38791525, 2024). "We hypothesize that the SWELL1/LRRC8 complex senses adipocyte hypertrophy in the setting of overnutrition and potentiates the insulin/PI3K/AKT2 signaling axis in a feed-forward amplifier manner." (PMID 36749637, 2023). "Though the defect in WAT is subtle, it may be a necessary predisposition to more severe WAT dysfunction, as well as for ectopic lipid deposition and insulin resistance in liver and skeletal muscle in prolonged states of overnutrition." (PMID 33411692, 2021). "Nutrient-induced toxicity due to overnutrition may lead to insulin-resistance in tissues such as the heart and the skeletal muscle, which normally responds to insulin for glucose uptake." (PMID 34576959, 2021). "Therefore, adiponectin-induced activation of AMPK helps to limit the consequences of overnutrition, thereby indirectly helping to restore insulin sensitivity." (PMID 34959666, 2021). "For example, increased substrate pressure and metabolic stress on β-cells caused by overnutrition and low-energy expenditure might stimulate some β-cell subpopulations towards proliferation through FOXO1 signaling in order to adjust to enhanced insulin demand." (PMID 33801681, 2021). "In addition, early overnutrition and control males showed similar glucose responses during insulin tolerance tests at P85, suggesting comparable degrees of insulin sensitivity." (PMID 30842440, 2019).
overnutrition (continued). "A possible mechanism could be that greater GWG reflects overnutrition in utero, thereby exposing the fetus to more glucose and fatty acids, which could increase fetal secretion of insulin and further lead to adiposity." (PMID 30695989, 2019). "Mitochondria are functionally and structurally linked to ER, which in condition of chronic overnutrition undergoes stress, which activates the unfolded protein response (UPR) which in turn activates the principal inflammatory pathways that impair insulin action." (PMID 29538286, 2018). "However, in cases of chronic overnutrition, the body can become less responsive to insulin, leading to a state known as insulin resistance." (PMID 29239299, 2017). "Overnutrition has been reported to activate hypothalamic IKKβ/NF-κB through endoplasmic reticulum stress in the hypothalamus region, which leads to the interrupted insulin and leptin signaling." (PMID 29025435, 2017). "Conversely, the insulin pathway may also target the inflammatory one, creating an inhibitory feedback that becomes active under conditions of overnutrition." (PMID 28912810, 2017). "Moreover, these diverse mechanisms for activation of mTORC1 by amino acids and INS act in a cooperative manner and provide a physiological explanation for increased mTORC1 signaling in response to overnutrition-related increases in nutrients and INS." (PMID 21977024, 2012). "Studies in larger cohorts of subjects might be needed to uncover changes in whole-body insulin sensitivity following overnutrition." (PMID 19781106, 2009). "Consuming a “modern” Western diet and overnutrition may increase insulin secretion." (PMID 39769002, 2024). "Taken together, these data suggest that activation of the PKCε pathway, by a short-term HFD, is triggered by PM-associated sn-1,2-DAG accumulation and that the sn-1,2-DAG/PKCε pathway may be the primary driver of impaired WAT insulin signaling in short-term overnutrition." (PMID 33411692, 2021). "Moreover, mitochondria are functionally and structurally linked to ER, which undergoes stress in conditions of chronic overnutrition, activating the unfolded protein response, which in turn activates the principal inflammatory pathways that impair insulin action." (PMID 29538286, 2018). "This study demonstrates that early postnatal overnutrition can have long-lasting effects on body weight and serum fatty acid profiles and can lead to impaired insulin signaling pathway in visceral white adipose tissue and skeletal muscle, which may play a major role in IR." (PMID 26302954, 2015). "While we did not see an association between baseline insulin sensitivity and responses to overfeeding there may be differences in how individuals can or cannot respond to overnutrition based on their baseline insulin sensitivity." (PMID 19781106, 2009). "β Cell functional adaptations are exemplified by attenuation of the insulin-secretory response following a prolonged fast and sensitization of GSIS during chronic overnutrition." (PMID 36821378, 2023). "Since the activation of the PI3K/Akt pathway in response to insulin was similar in hearts from control and overfed rats, these results suggest that this pathway may not be the one responsible for cardiac insulin resistance in this experimental model of early overnutrition." (PMID 32093229, 2020). "A second insulin tolerance test performed at P197 in LFD-fed mice only showed that both control and early overnutrition mice maintained insulin sensitivity." (PMID 30842440, 2019). "As PKC can be activated by lipid metabolites formed in metabolic tissues as a consequence of overnutrition, it can be speculated that PKC-mediated phosphorylation of AMPKα1 Ser487 underlies the reduced AMPK activity observed in tissues from mouse models of overnutrition and insulin-resistant people." (PMID 27784766, 2016).